HJURP (Holliday junction recognition protein)
Diseases named in the same sentence as HJURP in open-access papers (continued):
Sharing a sentence is not in itself a finding about the gene and the disease.
tumor (continued). "The volume and weight of tumor mass was significantly diminished in shHJURP group compared with negative control, but the effect of HJURP overexpression on tumor growth was not conspicuous in vivo like that of HJURP knockdown." (PMID 35173547, 2022). "Thus, we revealed that HJURP promotes PDAC cell proliferation, migration, and invasion in vitro, and facilitates tumor growth and metastasis in vivo." (PMID 32439850, 2020). "After 4 weeks, we found that the tumor volume and mean tumor weight were significantly lower in the HJURP knockdown group (lenti-HJURP#1) than in the negative control group." (PMID 30111352, 2018). "Furthermore, we analyzed the relationship between HJURP expression and clinicopathologic features of the HCC patients and found significant differences in age, tumor size and tumor stage." (PMID 30111352, 2018). "No significant improvement in accuracy was obtained by combining TG2 with HJURP or HIF-1α in either tumor cells or in stroma, whereas an important increase in accuracy (AUC 0.80, 95% CI 0.63–0.97) was obtained when HIF-1 α and HJURP stromal expression was considered together." (PMID 25243117, 2014). "Moreover, mRNA expressions of CA14, RPE65, IGSF1, SLC18 A2 and CPNE6 were significantly lower in PCa samples compared to benign samples, while HJURP, COMP, KRTAP5-1, VGF, SSTR1, LINC01612, NAALADL2-AS2, AMH and ARHGDIG were elevated in tumor samples (p < 0.05)." (PMID 40592939, 2025). "Interestingly, HJURP was overexpressed in ehCCA than para-tumor tissues, but this tendency was not statistically significant as to iCCA (P = 0.114)." (PMID 35965590, 2022). "We examined both cell lines by immunofluorescence following HJURP depletion and observed a striking enlargement of nucleus and micronucleus formation following HJURP depletion exclusively in the tumor-derived MCF7 cell line and not in the MCF10a cell line, suggesting an accumulation of aneuploidy." (PMID 28356341, 2017). "However, given the role of HJURP in depositing CENP-A at all centromeres, depleting it affects all chromosomes universally, and the massive aneuploidy that ensues has a net detrimental effect on the tumor." (PMID 28356341, 2017). "HJURP mRNA levels were significantly associated with estrogen receptor (ER), progesterone receptor (PR), Scarff-Bloom-Richardson (SBR) grade, age and Ki67 proliferation indices, but not with pathologic stage, ERBB2, tumor size, or lymph node status." (PMID 20211017, 2010). "Interestingly, while both tumor cells showed high cell death, the viability of non-tumoral cells were not significantly affected after HJURP silencing, which indicates that the maintenance of HJURP levels is more critical for the highly proliferating GBM cells than for control cells." (PMID 23638004, 2013). "Using the other markers (SLC6A8, HJURP, CCNE2), the detection of the spiked-in tumor cells was not possible due to high background signal from PBMCs and the low expression in the selected three cell lines, which results in equal Ct values in spiked and unspiked samples." (PMID 36831613, 2023). "Furthermore, our studies showed that the prognostic effect of HJURP mRNA level on survival is independent of the clinical factors, such as age, lymph node, pathological stage, SBR grade, ER, PR, tumor size, and the molecular subtypes." (PMID 20211017, 2010). "Similarly, CDCA3 and HJURP displayed reproducible negative correlations with distinct NSC derivatives (e.g., NSC685416, NSC709900), consistent with enhanced drug sensitivity in tumours with elevated expression." (PMID 41007424, 2025).
HJURP also shares sentences with these, for which no sentence is quoted: cholangiocarcinoma (6 papers); liver cancer (5); COVID-19 (3); gastric cancer (3); bladder urothelial carcinoma (2); colon cancer (2); pancreatic ductal adenocarcinoma (2); anaplastic gliomas (1); brain cancer (1); esophageal cancer (1); gastric tumors (1); head and neck cancer (1); hereditary disease (1); malignant glioma (1); mental retardation (1); metastatic prostate carcinoma (1); neuroblastoma (1); ovarian adenocarcinoma (1); prostatic adenocarcinoma (1); renal papillary cell carcinoma (1); sarcoma (1); skin tumors (1); uveal melanoma (1); viral infection (1).